EHD2 (EH domain containing 2)
Description:
ATP- and membrane-binding protein that controls membrane reorganization/tubulation upon ATP hydrolysis (By similarity). Plays a role in membrane trafficking between the plasma membrane and endosomes. Important for the internalization of GLUT4. Required for fusion of myoblasts to skeletal muscle myotubes. Required for normal translocation of FER1L5 to the plasma membrane (By similarity). Regulates the equilibrium between cell surface-associated and cell surface-dissociated caveolae by constraining caveolae at the cell membrane.
Synonyms: PAST2
Tractability: Antibody: UniProt places it where antibodies can reach, with high confidence; its Gene Ontology location is reachable by antibodies, with medium confidence; the Human Protein Atlas places it where antibodies can reach. PROTAC: ubiquitination databases record sites on it; its protein half-life has been measured.
Gene: Protein-coding gene on chromosome 19 (47,713,416 to 47,743,134, forward strand). Ensembl gene ENSG00000024422.
Subcellular location: Cell membrane; Membrane, caveola; Endosome membrane; Cytoplasm, cytosol
Subcellular location (Human Protein Atlas): Plasma membrane; Primary cilium; Primary cilium transition zone
Pathways (Reactome):
Hemostasis: Factors involved in megakaryocyte development and platelet production
Gene Ontology:
Molecular function: protein binding; nucleic acid binding; protein-macromolecule adaptor activity; calcium ion binding; GTP binding; identical protein binding; protein domain specific binding
Biological process: endocytic recycling; cilium assembly; plasma membrane tubulation; positive regulation of endocytic recycling; positive regulation of myoblast fusion; protein localization to plasma membrane
Cellular component: caveola; extracellular exosome; plasma membrane; recycling endosome membrane; cytosol; early endosome; endocytic vesicle; endosome membrane; membrane; nucleus; perinuclear region of cytoplasm
Genetic constraint (gnomAD): Loss-of-function variants: 27 observed, 36.38 expected, observed/expected ratio (o/e) 0.74, 90% interval 0.55 to 1.02. The upper end of that interval is the gene's LOEUF score, 1.02, which puts it in group 4 of 6, group 1 being the genes least tolerant of losing a copy. Missense variants: 673 observed, 738.93 expected, observed/expected ratio (o/e) 0.91, 90% interval 0.85 to 0.97. Synonymous variants: 342 observed, 322.02 expected, observed/expected ratio (o/e) 1.06, 90% interval 0.97 to 1.16.
Homologues: Orthologues: macaque EHD2 (99% identical), chimpanzee EHD2 (99% identical), dog EHD2 (99% identical), pig EHD2 (99% identical), guinea pig EHD2 (97% identical), rat Ehd2 (97% identical), mouse Ehd2 (97% identical), tropical clawed frog ehd2 (80% identical), zebrafish ehd2b (80% identical), zebrafish ehd2a (68% identical), Caenorhabditis elegans itsn-1 (13% identical), Drosophila melanogaster Eps-15 (13% identical), and 2 more. Paralogues in human: EHD3 (71% identical), EHD1 (70% identical), EHD4 (68% identical), SRL (25% identical), ITSN1 (20% identical), ITSN2 (20% identical), EPS15L1 (17% identical), EPS15 (17% identical), REPS1 (11% identical), REPS2 (9% identical).
Diseases named in the same sentence as EHD2 in open-access papers:
EHD2 is named in the same sentence as 38 diseases in open-access papers, as found by Europe PMC text mining. Sharing a sentence is not in itself a finding about the gene and the disease. The quoted sentences say what the papers report.
breast carcinoma (5 papers, 2017 to 2024). "EHD2 is overexpressed in a subset of breast cancer patients and is associated with metastasis and shorter survival." (PMID 36625722, 2023). "In apparent contradiction with in vitro data, multivariate analysis of two independent cohorts of breast cancer patients revealed that low EHD2 was in fact associated with good prognosis in the highly proliferative TNBC subtype." (PMID 32409676, 2020). "In this study, we found that the expression of EHD2 was significantly reduced in TNBC as compared to the other subtypes of breast cancers, and that the loss of EHD2 significantly enhanced the migration and the invasion of TNBC cells." (PMID 32409676, 2020). "EHD2 is associated with migration and invasion of tumor cells as a possible prognostic marker in esophageal and breast cancers." (PMID 28358874, 2017). "Low expression of EHD2 has been associated with poor overall survival of esophageal cancer and breast cancer patients." (PMID 28358874, 2017). "EHD2 and Caveolin-1/2 are co-overexpressed in breast cancers and EHD2 regulates cell surface caveolae." (PMID 36625722, 2023). "(B) Kaplan-Meier survival curves correlating positive/high (green) vs. low/negative (blue) nuclear (N=288 vs 458) or cytoplasmic (N=392 vs 352) EHD2 expression with Breast Cancer Specific Survival (BCSS)." (PMID 36625722, 2023). "Here, we show that overexpression of the EPS15-Homology Domain-containing 2 (EHD2) protein in a large subset of breast cancers (BCs), especially the triple-negative (TNBC) and HER2+ subtypes, correlates with shorter patient survival." (PMID 36625722, 2023). "In this study, we analyzed the significance of mRNA and protein levels of EHD2 in breast cancer prognosis." (PMID 32409676, 2020). "Accordingly, TNBC low EHD2 expressers were found to benefit the most from chemotherapy when compared to all subtypes of breast cancers." (PMID 32409676, 2020). "Scoring of staining intensity revealed that a low H-score of EHD2 expression was significantly associated with triple negative basal-like cancers, when compared to HER2 and luminal breast cancers." (PMID 32409676, 2020). "We examined EHD2 mRNA expression in a retrospective cohort of 526 breast cancer patients that was collected over the last 30 years." (PMID 32409676, 2020). "Altogether, these findings establish EHD2 mRNA and protein expression levels as key parameters in the control of breast cancer cell migration and invasion." (PMID 32409676, 2020). "The aim of this study was to assess the prognostic significance of EHD2 transcripts and protein expression levels in breast carcinomas." (PMID 32409676, 2020). "Changes in EHD2 expression levels revealed a correlation with IL-8 expression in breast cancer cell lines." (PMID 32409676, 2020). "A high correlation was observed between EHD2 mRNA and protein levels in triple negative basal-like breast cancer cell lines as reflected by the Pearson’s correlation index (r = 0.95)." (PMID 32409676, 2020). "To better understand the significance of variations of EHD2 expression in breast cancers, we selected the Hs578T, MDA-MB-231 and MDA-MB-436 TNBC cell lines that respectively express three representative levels of EHD2 transcripts i.e. high, medium, and low." (PMID 32409676, 2020). "Accordingly, we found that low EHD2 was a new independent prognostic factor in the subgroup of TNBC patients treated with chemotherapy compared to all other breast cancer subgroups." (PMID 32409676, 2020). "Under-expression of EHD2 mRNA and EHD2 protein has been observed in different cancers, including esophageal squamous cells carcinoma, breast cancer, glioma, and serous ovarian cancers compared to normal tissue samples." (PMID 28358874, 2017). "Dysregulation of EHD2 expression has been detected in various human cancers including esophageal squamous cell carcinoma, breast carcinoma, glioma, and ovarian serous carcinoma." (PMID 28358874, 2017).
breast carcinoma (continued). "Notably, EHD2 and CAV1 mRNAs were found to be coordinately expressed and jointly associated with shorter survival in basal breast cancer." (PMID 38959243, 2024). "Here, we examined EHD2 expression in breast cancer cell lines and breast cancer patients." (PMID 32409676, 2020). "Finally, TNBC low EHD2 expressers showed a positive response to chemotherapy compared with all subtypes of breast cancers." (PMID 32409676, 2020). "(B) KM plotter analysis of EHD2, CAV1 and CAV2 overexpression correlation with relapse-free survival (RFS) for upper vs. lower quartiles in basal-like breast cancer (PAM50-based) cohorts of TCGA, GEO, and GEA datasets." (PMID 36625722, 2023). "(C) Immunoblot analysis of coordinate EHD2 and CAV1 expression in immortal mammary epithelial cells and breast cancer cell lines." (PMID 36625722, 2023). "(A) Representative images of negative/low/high cytoplasmic and nuclear EHD2 IHC staining of a breast cancer tumor microarray (840 samples)." (PMID 36625722, 2023). "In breast cancer cells, RCN1 forms a complex with PIGX and RCN2 that negatively regulates the expression of ZIC family member 1 (ZIC1) and EH domain‐containing protein 2 (EHD2), promoting breast carcinogenesis." (PMID 37746742, 2023). "In alignment with our analysis on patient biopsies, measurement of EHD2 mRNA transcripts revealed that the majority (72%) of cell lines derived from triple negative basal-like breast cancers had low EHD2 mrna expression compared to non-cancer epithelial cell lines." (PMID 32409676, 2020).
Obesity (4 papers, 2019 to 2023). Accumulation of substantial excess body fat. "Similarly, EHD2, the EH domain-containing 2, is a known obesity-associated gene implicated in GLUT4 endocytosis and in the maintenance of intracellular lipid metabolism in adipocytes." (PMID 36535927, 2022). "In conclusion, these data highlight the importance of EHD2 for the integrity of the plasma membrane milieu, insulin receptor stability, and downstream insulin receptor signaling events, involved in glucose uptake and ultimately underscore its role in insulin resistance and obesity." (PMID 37703099, 2023).
esophageal cancer (3 papers, 2013 to 2022). A primary or metastatic malignant neoplasm involving the esophagus. "Data from the TCGA database also showed that EHD2 was overexpressed in other cancer types such as esophageal carcinoma (ESCA), kidney renal clear-cell carcinoma (KIRC), and intrahepatic cholangiocarcinoma (ICC)." (PMID 35177645, 2022). "The typical case showed that low expression of EHD2 was correlated with low E-cadherin in the same esophageal cancer specimen." (PMID 23354948, 2013).
esophageal squamous cell carcinoma (3 papers, 2013 to 2020). Esophageal squamous cell carcinoma (ESCC) is a type of esophageal carcinoma (EC) that can affect any part of the esophagus, but is usually located in the upper or middle third. "Downregulation of EHD2 has been associated with poor prognosis in esophageal squamous cell carcinoma, hepatocellular carcinoma and breast cancer." (PMID 32409676, 2020). "Interference of EHD2 led to esophageal squamous cell carcinoma cells TE1 migration significantly." (PMID 23354948, 2013). "We investigated the expression of EHD2 in human esophageal squamous cell carcinoma (ESCC) and the EHD2 expression to study the therapeutic effect of chemotherapy drugs." (PMID 23354948, 2013).
glioma (3 papers, 2017 to 2024). A benign or malignant brain and spinal cord tumor that arises from glial cells (astrocytes, oligodendrocytes, ependymal cells). "Subsequent cell function test results showed that inhibition of FCGR2A or EHD2 significantly represses proliferation, migration, and invasion of glioma cells, and reduces the expression of mesenchymal marker genes." (PMID 33875619, 2021). "In contrast, KIF5A and EHD2 displayed differential expression between GBM and all other gliomas." (PMID 38638676, 2024). "Using five existing glioma cell lines in the research group to carry out qRT-PCR, it was found that FCGR2A was expressed at a relatively high level in LN18 and T98G cells, whereas EHD2 was expressed at a high level in U251 and SNB19 cells." (PMID 33875619, 2021). "The remaining two genes, FCGR2A and EHD2, have not been studied in gliomas." (PMID 33875619, 2021).
hepatocellular carcinoma (3 papers, 2020 to 2023). A malignant tumor that arises from hepatocytes. "Reduced EHD2 expression was reported in esophageal, colorectal, breast, and hepatocellular cancers, with in vitro knockdown or overexpression studies supporting a tumor suppressive role for EHD2." (PMID 36625722, 2023).
breast tumors (2 papers, 2020 to 2023). "The mRNAs for EHD2 and Caveolin-1/2, structural components of caveolae, show co-overexpression across breast tumors, predicting shorter survival in basal-like BC." (PMID 36625722, 2023). "Immunohistochemical analysis of a tissue microarray (TMA) of 423 invasive breast tumors revealed that EHD2 was localized in the nucleus of epithelial tumor cells and stromal cells i.e. fibroblasts, inflammatory, and endothelial cells." (PMID 32409676, 2020). "Notably, a recent study, while it reported the depletion of EHD2 to increase the oncogenic traits of BC cell lines in vitro, found low EHD2 expression in breast tumors to specify good prognosis and better chemotherapy response." (PMID 36625722, 2023).
intracerebral hemorrhage (2 papers, 2018 to 2022). A cerebrovascular disorder characterized by bleeding into one or both cerebral hemispheres including the basal ganglia and the cerebral cortex. "It has been found that in intracerebral hemorrhage (ICH), microglial activation marker CD68 was co-located with EHD2, a member of the Eps15 homology domain (EH domain) family." (PMID 36712438, 2022).
lymph node metastasis (2 papers, 2017 to 2023). "Increased EHD2 mRNA expression level was associated with extrathyroidal extension (p < 0.001), pT3-4 (p < 0.001), lymph node metastasis (p < 0.001), higher risk of recurrence (p < 0.001), and BRAF V600E (p < 0.001)." (PMID 28358874, 2017). "Metabolic proteins, such as EHD2 and CAVIN1, were expressed at higher levels in the LN+ group than in the LN- group, and EHD2 and CAVIN1 in the PDF were positively correlated with lymph node metastasis." (PMID 36671802, 2023).
triple-negative breast carcinoma (2 papers, 2020 to 2023). An invasive breast carcinoma which is negative for expression of estrogen receptor (ER), progesterone receptor (PR), and human epidermal growth factor receptor 2 (HER2). "In two distinct cohorts of TNBC patients, we found that EHD2 downregulation was associated with triple negative breast cancer and was a new independent prognostic factor of MFS." (PMID 32409676, 2020). "We found that the decrease of EHD2 expression was correlated with enhanced proliferation, migration and invasion of triple negative breast cancer cells." (PMID 32409676, 2020).
Autoimmunity (1 paper, 2023). The occurrence of an immune reaction against the organism's own cells or tissues. "EHD2-sc-mTNFR2, the agonist used in this study, was used successfully to treat EAE symptoms, with its positive effects attributed in part to the promotion of peripheral Treg expansion and subsequent suppression of autoimmunity." (PMID 37122019, 2023).
COVID-19 (1 paper, 2022). A disease caused by infection with severe acute respiratory syndrome coronavirus 2. "Importantly, EHD2 is underexpressed in obese patients, a known risk comorbidity for severe COVID-19." (PMID 36818472, 2022).
epilepsy (1 paper, 2024). A brain disorder characterized by episodes of abnormally increased neuronal discharge resulting in transient episodes of sensory or motor neurological dysfunction, or psychic dysfunction. "In the literature one additional de novo (likely) pathogenic EHD2 missense change (c.5855T > C p.(Met1952Thr)) in an individual with mild ID, epilepsy and marfanoid features has been reported." (PMID 39028335, 2024).
esophageal tumors (1 paper, 2013). "Lower expression of EHD2 was observed in malignant esophageal tumors (T) than in adjacent normal tissues (N)." (PMID 23354948, 2013).
germ cell tumor (1 paper, 2012). A benign or malignant, gonadal or extragonadal neoplasm that originates from germ cells. "Likewise, EHD2, ITGA8 and EMP1 has also been identified as tumor suppressor genes that when altered is associated with highly malignant ovarian cancers and germ cell tumors." (PMID 22737227, 2012).
glioblastoma (1 paper, 2024). The most malignant astrocytic tumor (WHO grade IV). "The mRNA expression of EPS15 and KIF5A was significantly downregulated in both the TCGA and REMBRANDT glioblastoma datasets, and EHD2 was upregulated in both datasets." (PMID 38638676, 2024).
head and neck squamous cell carcinoma (1 paper, 2019). A squamous cell carcinoma that arises from any of the following anatomic sites: lip and oral cavity, nasal cavity, paranasal sinuses, pharynx, larynx, and salivary glands. "Yadav et al46 found that myoferlin is bound to EHD2 protein and modulates the IL‐6/STAT3 signalling pathway, which regulates the expression of IL‐6/STAT3 downstream genes, including snail and nanog, in head and neck squamous cell carcinoma (HNSCC) cell lines." (PMID 31475450, 2019).
itch (1 paper, 2017). "In three itch models, Fos and Ehd2 were up-regulated whereas Corin, 4921511E18Rik and 4930423020Rik were down-regulated." (PMID 29088797, 2017). "On comparing three itch models, we found that the various pruritogens yielded consistent results, and in three itch models, Fos and Ehd2 were up-regulated whereas Corin, 4921511E18Rik and 4930423020Rik were down-regulated." (PMID 29088797, 2017).
lung carcinoma (1 paper, 2023). "EFEMP2 and EHD2 have been reported to inhibit the invasion and metastasis of lung cancer cells by regulating the epithelial-mesenchymal transition (EMT) process and MMP activity." (PMID 37291533, 2023).
malignant glioma (1 paper, 2023). A grade III or grade IV glioma arising from the central nervous system. "On the contrary, EHD2 overexpression was found as a component of a mesenchymal signature in malignant gliomas with shorter survival, and knockdown analyses showed the EHD2 requirement for cell proliferation, migration, and invasion." (PMID 36625722, 2023).
memory impairment (1 paper, 2022). "It was shown that EHD2-scTNFR2 protects mice from acute neurodegeneration and memory impairment, and the murine ortholog EHD2-sc-mTNFR2 induces the expansion of Tregs with anti-inflammatory responses." (PMID 35057080, 2022).
metastasis (1 paper, 2017). The spread or migration of cancer cells from one part of the body (where they first appeared) to another. "Increased EHD2 mRNA expression was significantly associated with extrathyroidal extension (p < 0.001), pT3-4 (p < 0.001), lymph node metastasis (p < 0.001), higher risk of recurrence (p < 0.001), BRAF V600E (p < 0.001), and BRAFV600E-like PTC (p < 0.001)." (PMID 28358874, 2017).
osteosarcoma (1 paper, 2024). A usually aggressive malignant bone-forming mesenchymal neoplasm, predominantly affecting adolescents and young adults. "Little is known about the role of EHD2 in the bone, although its expression has been reported in osteoblastic-cell lines where it is thought to contribute to tumor suppression in the context of osteosarcoma." (PMID 38776873, 2024).
pulmonary fibrosis (1 paper, 2023). Chronic progressive interstitial lung disorder characterized by the replacement of the lung tissue by connective tissue, leading to progressive dyspnea, respiratory failure, or right heart failure. "Caveolin 1 has been found to prevent bleomycin-induced fibrosis by inhibiting inflammasome activation, although the roles of Cavin2 and Ehd2 in pulmonary fibrosis are not well-defined." (PMID 37852965, 2023).
renal cell carcinoma (1 paper, 2024). "Circular RNA EHD2 (CircEHD2) from renal cell carcinoma cell-derived EVs activates CAFs to accelerate the growth of renal cell carcinoma cells via the circEHD2/YWHAH/YAP/SOX9 signaling pathway." (PMID 39759028, 2024).